MIR524 (microRNA 524)
Synonyms: hsa-mir-524; MIRN524; mir-524
Gene: MicroRNA gene on chromosome 19 (53,711,002 to 53,711,088, forward strand). Ensembl gene ENSG00000283289.
Gene Ontology:
Biological process: miRNA-mediated post-transcriptional gene silencing
Homologues: Orthologues: chimpanzee ptr-mir-524 (100% identical), macaque mml-mir-524 (92% identical). Paralogues in human: MIR521-1 (87% identical), MIR518D (86% identical), MIR518F (86% identical), MIR518C (85% identical), MIR518E (85% identical), MIR523 (84% identical), MIR516A1 (82% identical), MIR522 (82% identical), MIR525 (82% identical), MIR516A2 (80% identical), MIR517A (80% identical), MIR519A2 (80% identical), and 12 more.